EBI3 (Epstein-Barr virus induced 3)
Diseases named in the same sentence as EBI3 in open-access papers (continued):
Sharing a sentence is not in itself a finding about the gene and the disease.
melanoma (6 papers, 2021 to 2025). A malignant, usually aggressive tumor composed of atypical, neoplastic melanocytes. "Using the coefficients obtained by multivariate Cox analysis, the risk score of melanoma patients was calculated according to the following formula: risk score = (−0.097) × A2M + (−0.185) × NAMPT + (−0.123) × LIF + (−0.247) × EBI3 + (−0.170) × ERAP1." (PMID 35326741, 2022). "In this study, we used bioinformatics to analyze the expression of EBI3 in pan-cancer and verified its expression level in melanoma cells by reverse transcription-quantitative polymerase chain reaction (RT-qPCR)." (PMID 39726752, 2024). "Transwell migration/invasion assay was adopted to evaluate the migration and invasion of melanoma cells following the knockdown of EBI3." (PMID 39726752, 2024). "Epstein-Barr virus induced gene 3 (EBI3), a member of the IL-12 family, is known to be involved in malignant progression in a variety of cancers, but its role in melanoma is unclear." (PMID 39726752, 2024). "Subsequently, the expression levels of EBI3 in melanoma cells were quantified in the beginning, and the highest expression of EBI3 was seen in MV3 cells (p-value < 0.01)." (PMID 39726752, 2024). "The relevant results have demonstrated that the concentrations of these specific cytokines including IL-35, IL-4 and IL-13 were all higher in melanoma cells with the presence of EBI3-specific small interfering RNA (p-value < 0.05)." (PMID 39726752, 2024). "At 48 h, the reduced number of both migrated and invaded melanoma cells was clearly seen following the knockdown of EBI3 (p-value < 0.01)." (PMID 39726752, 2024). "Toward this end, the expression pattern of EBI3 in melanoma was predicted and the effects of EBI3 on the malignant phenotypes and immune of melanoma cells were investigated based on some basic cellular assays." (PMID 39726752, 2024). "The aim of this study was to explore the effects of EBI3 on the malignant phenotype melanoma to reveal its potential as a therapeutic target." (PMID 39726752, 2024). "With the purpose of exploring the involvement of EBI3 in melanoma, the pan-cancer EBI3 expression pattern was predicted and downloaded." (PMID 39726752, 2024). "ELISA was used to investigate the potential effects of EBI3 knockdown on the immune response of melanoma cells via calculating the concentrations of specific cytokines." (PMID 39726752, 2024). "The specific mechanisms of action of these cytokines will be further explored in subsequent studies to confirm their specific contributions in the regulation of melanoma progression by EBI3." (PMID 39726752, 2024). "First, this study explored the effects of EBI3 on the malignant phenotype and immune response of melanoma only at the cellular level." (PMID 39726752, 2024). "In our current study, we further explored the involvement of EBI3 in melanoma based on some preliminary investigations using melanoma cells cultured in vitro." (PMID 39726752, 2024). "high expression of EBI3 promoted proliferation, migration and invasion of melanoma cells, while its knockdown inhibited these malignant behaviors and induced apoptosis." (PMID 39726752, 2024). "In our current work, we further explored the effects of EBI3 in the malignant phenotype of melanoma cells and on the tumor microenvironment." (PMID 39726752, 2024). "The modulation of phenotypes as well as these proteins belonging to cadherin and BCL2 families via EBI3 has further completed the discovery highlighting the involvement of EBI3 in melanoma." (PMID 39726752, 2024). "Then the corresponding results from immunofluorescence assay has suggested that the knockdown of EBI3 in melanoma cells contributed to the reduced CD206 fluorescence intensity yet the increased CD86 fluorescence intensity in these induced macrophages from THP-1 monocytes (p-value < 0.05)." (PMID 39726752, 2024).
melanoma (continued). "EBI3 was evidently highly-expressed in melanoma, and silencing of EBI3 could visibly suppress the survival and migration/invasion of melanoma cells, concurrent with the increased levels of BAX and CDH1 and the decreased expressions of BCL2 and CDH2." (PMID 39726752, 2024). "Relevant results have demonstrated that EBI3 was higher expressed in melanoma and the silencing of EBI3 using commercial small interfering RNAs could suppress the malignant phenotypes of melanoma cells as well as modulate the macrophage polarization." (PMID 39726752, 2024). "Here, we expanded the discoveries concerning the cytokines in melanoma based on some relevant results in our current study, where it was evident that the levels of IL-4, IL-13 and IL-35 in melanoma were all elevated following the silencing of EBI3." (PMID 39726752, 2024). "It was seen in THP-1 monocytes-induced macrophages that the silencing of EBI3 in melanoma cells could visibly upregulate the expression of c-GAS and promote the phosphorylation of both STING and IRE1α (p-value < 0.05)." (PMID 39726752, 2024). "Our current study has hinted that EBI3 silencing could suppress the proliferation, migration and invasion of melanoma cells, concurrent with the diminished expression of CDH2 and BCL2 yet the upregulated expression of CDH1 and BAX." (PMID 39726752, 2024). "This study provides a new rationale for EBI3 as a potential therapeutic target for melanoma." (PMID 39726752, 2024). "In summary, the present study revealed the critical role of EBI3 in melanoma." (PMID 39726752, 2024). "While exploring the specific malignant phenotypes of EBI3-silenced melanoma cells in vitro, a series of assays like CCK-8 and Transwell were adopted, revealing that the silencing of EBI3 could suppress the proliferation and metastasis of melanoma cells." (PMID 39726752, 2024). "Here, relevant results have demonstrated that EBI3 was highly-expressed in melanoma cells and silencing of EBI3 could modulate the malignant behaviors and immune response in melanoma." (PMID 39726752, 2024). "Thus far, 8 out of 21 GLI targets we chose to validate—KRT16, S100A9, SOX9, BIRC7, EBI3, FLG, SAMMSON and SPRY2—were already implicated in melanoma pathogenesis." (PMID 36139698, 2022). "In addition, the genes EBI3, GH1, SOX9, RET, and SPRY2 are also good candidates for HH-GLI targets but exhibited a less uniform expression pattern in these melanoma cell lines." (PMID 36139698, 2022). "Moreover, the RT-PCR analysis in our clinical samples demonstrated that EBI3, ERAP1, and NAMPT mRNA expression levels were significantly upregulated in melanoma tissues compared to normal tissues." (PMID 35326741, 2022). "These evidences indeed proved the involvement of EBI3 in diverse cancers; however, the specific involvement of EBI3 in melanoma has not been explored, except a preliminary study based on The Cancer Genome Atlas (TCGA) hinting EBI3 as a potential biomarker in metastatic melanoma." (PMID 39726752, 2024). "Finally, although this study observed changes in IL-35, IL-4, and IL-13 levels after knockdown of EBI3, the specific role of these cytokines in melanoma was not analyzed in detail." (PMID 39726752, 2024). "In melanoma pretreatment tumors, CD4+ T cells from nonresponders had significantly higher activation (for example, TIMD4/TIM3, OX40/EBI3, HLA) and cell cycle cGEP usage (P < 0.05 two-tailed t-test)." (PMID 40903640, 2025). "The results demonstrated that EBI3, ERAP1, and NAMPT mRNA levels were upregulated in melanoma tissues, while A2M and LIF were not insignificant." (PMID 35326741, 2022). "Activation and cell cycle cGEPs were elevated in pretreatment nonresponders of melanoma and NMSC (meta-analysis P < 0.05 for CellCycle-G2M, CellCycle-Late-S, TIMD4/TIM3, exhaustion, ICOS/CD38, OX40/EBI3 and HLA) and in the combined CRC cohort (P < 0.05 for all)." (PMID 40903640, 2025).
inflammatory bowel disease (5 papers, 2011 to 2022). A spectrum of small and large bowel inflammatory diseases of unknown etiology. "The gene and protein expression levels of EBI3 and p35, which are the two subunits of IL-35, were significantly higher in the intestinal mucosa of patients with inflammatory bowel disease (IBD) compared to that of healthy controls." (PMID 28553015, 2017). "Furthermore, in the absence of EBi3 or p35 subunit production, Treg cells are unable to resolve gut inflammation in mouse inflammatory bowel disease (IBD)." (PMID 20981280, 2011).
lupus (5 papers, 2017 to 2025). "In particular, IL-39 has been implicated in the pathogenesis of murine lupus because shRNA-mediated knockdown of p19/EBI3 in B cells followed by adoptive cell transfer suppressed lupus-like disease." (PMID 33259477, 2020). "Other than IL-23, another p19-related heterodimeric cytokine IL-39, which consists of p19 and EBI3, was also identified and shown to be secreted from activated B cells to activate neutrophils, resulting in inflammatory responses in lupus-like model mice." (PMID 33664371, 2021). "There is evidence that IL-39 is associated with lupus immunopathogenicity in mice because shRNA-mediated knockdown of the p19 or EBI3 subunits in GL7+ B cells followed by adoptive transfer attenuated inflammation in lupus-like mice." (PMID 33259477, 2020). "However, the difficulty of predicting the immunological outcome of various combinations of α/βIL-12 subunit proteins is underscored by the recent discovery of IL-39, a novel pairing of Ebi3 and IL-23p19 that mediates pro-inflammatory responses in Lupus-like mice." (PMID 28959012, 2017).
psoriasis (5 papers, 2016 to 2023). An autoimmune condition characterized by red, well-delineated plaques with silvery scales that are usually on the extensor surfaces and scalp. "Flow cytometry also revealed increased populations of CD4+EBI3+p35+ and CD19+EBI3+p35+ cells in the peripheral blood of patients with psoriasis." (PMID 36969174, 2023). "The number of EBI3+p35+ cells was also significantly increased in the peripheral blood of patients with psoriasis." (PMID 36969174, 2023). "Immunohistochemical analysis showed that IL-23Ap19 and EBI3 expressions were upregulated in the psoriasis skin lesions." (PMID 34884474, 2021). "Further investigation is required to clarify the function of keratinocyte-derived IL-23Ap19 and EBI3 in psoriasis." (PMID 34884474, 2021). "Further investigation of the role of keratinocyte-derived IL-23Ap19 and EBI3 is required to clarify the pathogenesis of psoriasis." (PMID 34884474, 2021). "Moreover, the expressions of IL-23Ap19 and EBI3 were suppressed by dexamethasone, vitamin D3, and acitretin, which are commonly used for psoriasis therapy." (PMID 34884474, 2021). "To investigate whether human epidermal keratinocytes express IL-23Ap19 and EBI3 in psoriasis, we first immunostained normal skin and lesional psoriatic skin sections with polyclonal rabbit anti-IL-23Ap19 antibody and monoclonal mouse anti-EBI3 antibody." (PMID 34884474, 2021). "While EBI3, as a component of the suppressive cytokines IL-35 and IL-27, is upregulated in acute inflammation, its expression decreases in chronic inflammatory diseases like psoriasis, allergic asthma, and allergic rhinitis." (PMID 31955243, 2020). "EBI3 might be a therapeutic target for psoriasis in the future." (PMID 34884474, 2021). "Even if we cannot exclude the hypothesis that there was a local problem on Ebi3 detection by RNASeq analysis at d3, these results firmly suggest that it is IL-23 and not IL-39 which is regulated in an IL-36–dependent, KC36-dependent manner at d3 of Aldara-induced psoriasis-like dermatitis." (PMID 32345660, 2020). "Importantly, Ebi3 expression could not be detected at d3, which corresponds to the IL-36–dependent KC36-dependent regulation of both IL-23 subunits, suggesting that it is IL-23 and not IL-39 which exerts functions at d3 of Aldara-induced psoriasis-like dermatitis." (PMID 32345660, 2020).
allergic rhinitis (4 papers, 2017 to 2021). Inflammation of the nasal mucous membranes caused by an IgE-mediated response to external allergens. "In contrast, EBI3 polymorphisms have been associated with ulcerative colitis, pulmonary tuberculosis, chronic rhinosinusitis, and allergic rhinitis." (PMID 28321150, 2017). "Previous studies have reported that this genetic variation is related to the susceptibility of Alzheimer's disease and Graves' disease, while EBI3 genetic variation may affect the risk of allergic rhinitis (AR) and tuberculosis in Chinese." (PMID 33407151, 2021). "EBI3 rs428253 had a related effect on Chinese Han patients with allergic rhinitis." (PMID 34950136, 2021).
atherosclerosis (4 papers, 2012 to 2025). A disease characterized by the build-up of fatty material and calcium deposition in the arterial wall resulting in partial or complete occlusion of the arterial lumen. "The Ebi3 and p35 subunits have been identified as being present in theatherosclerotic aorta, and in mouse models predisposed to atherosclerosis, theloss of the Ebi3 subunit gene aggravates the disease." (PMID 40160593, 2025). "The two subunits of IL-35, EBI3 and p35, are strongly expressed in human advanced plaque, suggesting a potential role of IL-35 in atherosclerosis and coronary artery disease (CAD)." (PMID 23285065, 2012). "Specifically, EBI3 and p35 are strongly expressed in advanced atherosclerotic plaque in humans and can be up-regulated by TNF-α and IFN-γ stimulation in cultured human primary aortic smooth muscle cells, suggesting IL-35 may be involved in atherosclerosis progression." (PMID 23285065, 2012).
breast carcinoma (4 papers, 2016 to 2024). "In the meantime, upregulated EBI3 expression level was revealed to share correlation with the adverse clinical outcome and malignant progression in breast cancer patients." (PMID 39726752, 2024). "Furthermore, EBI3 blocking suppressed CRC cell proliferation through the gp130/Stat3 pathway, which mediated cell survival in various tumor, such as gastric cancer, breast cancer, hepatocellular carcinoma, and also CRC." (PMID 27247488, 2016).
diffuse large B-cell lymphoma (4 papers, 2011 to 2023). "In previous analyses, we observed that one subunit of IL-27, EBI3, was expressed at high levels by tumor cells in specific forms of lymphomas such as Hodgkin lymphoma, EBV or HTLV1-associated lymphoproliferative diseases and diffuse large B-cell lymphomas." (PMID 24130734, 2013). "These included CD40, TRAF1, EBI3, and ICAM1, which were previously established as TES1 target genes in studies of cell lines overexpressing LMP1, including BL-41 Burkitt and BJAB diffuse large B-cell lymphoma models." (PMID 38009935, 2023). "Previously, we had evidenced that EBI3 is selectively overexpressed by tumor cells in the most frequent type of non-Hodgkin lymphoma among adults, diffuse large B-cell lymphoma (DLBCL), but not in another type of mature aggressive B-cell lymphoma, Burkitt lymphoma." (PMID 31316915, 2019).
gastric cancer (4 papers, 2016 to 2025). A primary or metastatic malignant neoplasm involving the stomach. "In addition, further studies are necessary to investigate the underlying mechanisms by which EBI3 influences the invasion and metastasis of gastric cancer cells." (PMID 39291183, 2022). "While rhIL-35 did not directly impact the angiogenesis of HUVEC in vitro tube-forming assays, the supernatant from gastric cancer cells overexpressing IL-35, EBI3, and IL-12A notably enhanced HUVEC angiogenesis." (PMID 39974277, 2025). "Expression of EBI3 in gastric cancer (GC) cell lines, GC tissues, and corresponding adjacent tissues were detected by qRT-PCR, Western blot, or immunohistochemistry." (PMID 39291183, 2022). "The EBI3 expression level was the lowest in MKN-45 and was significantly higher in BGC-823 and MGC-803 than other gastric cancer cell lines (P < 0.05)." (PMID 39291183, 2022).
preeclampsia (4 papers, 2012 to 2019). Preeclampsia is a hypertensive disorder of pregnancy that is characterized by new-onset hypertension with proteinuria presenting after 20 weeks of gestation, and depending on mild or severe forms may initially present with severe headache, visual disturbances, and hyperreflexia. "As EBI3 expression in extravillous trophoblast cells is to be tightly regulated, it is important to investigate the role of increased EBI3 in preeclampsia." (PMID 22929622, 2012). "Interestingly, a recent study has reported elevated expression of EBI-3 (a chain of IL-35 heterodimer) in decidua from pregnant women with preeclampsia." (PMID 31897391, 2019).
viral infection (4 papers, 2017 to 2022). "The 8-gene signature included three genes over-expressed in bacterial infections (SMARCD3, ICAM1, EBI3; “bacterial genes”) and five over-expressed in viral infections (JUP, SUCLG2, IFI27, FCER1A, HESX1; “viral genes”)." (PMID 36543117, 2022). "Significant reductions in IL-10-producing CD4+ and CD8+ T cells are observed during viral infection in il27ra-/- and ebi3-/- mice compared to their WT counterparts." (PMID 35634328, 2022). "In the context of viral infection, NK cells from ebi3-/- and il27Ra-/- mice exhibited significant reductions in IFNγ production during the early phase of IAV infection compared to WT controls." (PMID 35634328, 2022).
Hodgkins lymphoma (3 papers, 2013 to 2022). A heterogeneous group of malignant lymphoid neoplasms of B-cell origin characterized histologically by the presence of Hodgkin and Reed-Sternberg (HRS) cells in the vast majority of cases. "EBI3 was associated with several human malignancies and detected in EBV-associated tumors, nasopharyngeal carcinoma (NPC), and Hodgkin lymphoma (HL) to inhibit an effective antitumor, independently of its association to IL-27p28." (PMID 27247488, 2016).
septic peritonitis (3 papers, 2012 to 2021). Septic peritonitis is an inflammatory condition of the peritoneum that occurs secondary to microbial contamination. "Mice deficient for the EBI3 subunit of IL-27 were resistant to CLP-induced septic peritonitis, and EBI3-/- mice displayed enhanced neutrophil migration and oxidative burst capacity after CLP." (PMID 34079555, 2021). "Furthermore, genetic ablation of EBI3 or neutralization of IL-27 via a soluble IL-27 receptor fusion protein is protective in a murine model of septic peritonitis." (PMID 23107287, 2012).
B cell lymphomas (2 papers, 2011 to 2019). "First, we analyzed EBI3 gene expression level in gene profiling studies performed in mature aggressive B-cell non-Hodgkin lymphomas that were available on Gene Expression Omnibus (GEO) of the National Center for Biotechnology Information." (PMID 21931777, 2011). "In previous immunohistochemical studies, we showed that Epstein-Barr virus (EBV)-induced gene 3 (EBI3), a molecule related to the p40 subunit of interleukin (IL)-12, exhibited a restricted expression profile among B-cell lymphomas." (PMID 21931777, 2011). "The factors regulating EBI3 expression in B-cell lymphomas remain to be established." (PMID 21931777, 2011). "We found that EBI3, which was originally characterized as a gene induced in EBV-transformed B cells by the viral oncogene LMP1, was also expressed in certain non-EBV-associated B-cell lymphomas such as DLBCL." (PMID 21931777, 2011).
Burkitt lymphoma (2 papers, 2011 to 2019). A rare form of malignant mature B-cell non-Hodgkin lymphoma. "We first investigated whether, similar to EBI3, p35 is selectively overexpressed in DLBCL compared to Burkitt lymphoma." (PMID 31316915, 2019).